NQO1 (NAD(P)H quinone dehydrogenase 1)
Diseases named in the same sentence as NQO1 in open-access papers (continued):
Sharing a sentence is not in itself a finding about the gene and the disease.
pancreatic cancer (46 papers, 2012 to 2026). "Nqo1 is overexpressed in pancreatic tumour versus the associated normal tissue; however, catalase expression reduces in comparison to the levels related to normal pancreas tissues." (PMID 35180880, 2022). "Surprisingly, in previous studies, it has been proved that all of our defined switch genes, including Lamc2, Klk1, Nqo1, Aox1, Tspan1, and Cxcl12, are closely associated with the pancreatic cancer’s progression." (PMID 35180880, 2022). "In contrast, NQO1-deficient cell lines, B16 (melanoma) and Panc02 (pancreatic cancer), were resistant to β-lap exposure." (PMID 31324798, 2019). "In NQO1-expressing cells, increased reactive oxygen species cause single-stranded DNA damage, while NQO1 is expressed at increased levels in many cancers, including pancreatic cancer." (PMID 37664430, 2023). "Importantly, at the mechanistic level, our data strongly suggest that reactive oxygen species produced by NQO1-dependent redox cycling of KP372-1 cause massive DNA damage in pancreatic cancer cells within two hours of treatment." (PMID 33214574, 2020). "In studies with BxPc-3 human pancreatic cancer cells the association of NQO1 with mitotic spindles appeared to be unchanged in the presence of NQO1 inhibitors ES936 or dicoumarol suggesting that NQO1 can associate with the mitotic spindle and still retain catalytic activity." (PMID 22984577, 2012). "Functional studies support this potential: inhibition of NQO1 with dicumarol increased intracellular superoxide levels and suppressed pancreatic cancer cell growth in vitro." (PMID 41007761, 2025). "In an earlier study, dicoumarol, a potent inhibitor of NQO1, was shown to suppress formation of pancreatic cancer cell colonies on soft agar 60 and decrease the viability and proliferation rates of HeLa cells." (PMID 36793872, 2023). "Accumulation of p62 and increased positive staining of NQO1 molecules related to autophagy dysfunction were detected in pancreatic acinar cells in the fatty area, acinar-ductal metaplasia, and pancreatic cancer cells." (PMID 37664430, 2023). "In pancreatic cancer, it is highly expressed in pancreatic cancer cells and PanIN, and NQO1 inhibitors suppress the progression of pancreatic cancer." (PMID 37664430, 2023). "Compound 3a induced apoptosis in ex vivo cultures of pancreatic cancer xenografts with a high NQO1/NRF2 activation, and inhibited the biosynthesis of amino acids, including asparagine and methionine." (PMID 37446864, 2023). "In particular, a 100-fold increase in NQO1 expression was found in pancreatic cancer, the most lethal cancer type with a 5-year overall survival rate below 10%." (PMID 37570646, 2023). "The elevated Nqo1 expression in the pancreatic tumour is also represented in numerous early kinds of cancers like pancreatic intraepithelial neoplasia (PanINs)." (PMID 35180880, 2022). "Sestrin2 overexpression increased the protein expression of p-Nrf2, HO-1, and NQO-1 in pancreatic cancer cells compared with that in the control group, and the expression of the Nrf-2 binding protein Keap1 decreased." (PMID 34306067, 2021). "IQ9 is an analogue of ES936, an NQO1 inhibitor developed from EO9 which has been shown to be a potent anticancer agent against pancreatic cancer cells." (PMID 33768386, 2021). "Increased NQO1/decreased catalase expression is observed in pancreatic intraepithelial neoplasia, precursor lesions of pancreatic cancer." (PMID 34789190, 2021). "Elevated expression of NAD(P)H:Quinone Oxidoreductase 1 (NQO1) is frequent in pancreatic cancer, allowing for tumor-selective targeting, and NQO1-bioactivatable compounds have been shown to be highly effective against lung and pancreatic cancer." (PMID 33214574, 2020). "Here, we show that KP372-1 sensitizes NQO1-expressing pancreatic cancer cells and spares immortalized normal pancreatic duct cells, hTERT-HPNE." (PMID 33214574, 2020).
pancreatic cancer (continued). "Collectively, these data strongly support a robust DNA damage response instigated by KP372-1 in NQO1-expressing pancreatic cancer cells." (PMID 33214574, 2020). "Nonetheless, these data clearly suggest that KP372-1 treatment induces PARP1 hyperactivation in NQO1-expressing pancreatic cancer cells." (PMID 33214574, 2020). "NQO1 overexpression has been reported in a variety of solid tumors including lung and pancreatic cancer, and targeting NQO1 has emerged as a promising strategy." (PMID 33214574, 2020). "Elevated expression of NAD(P)H:quinone oxidoreductase 1 (NQO1) is frequent in pancreatic cancer, and it offers promising tumor-selective targeting." (PMID 33214574, 2020). "This study further demonstrates high levels of NQO1 expression in patient sample data obtained from Oncomine as well as from some of the commonly utilized pancreatic cancer cell lines." (PMID 33214574, 2020). "Within the database, we found that multiple studies reported significantly elevated NQO1 mRNA levels, ranging from three to tenfold, in pancreatic cancer compared to normal pancreatic tissue from a considerable number of patients." (PMID 33214574, 2020). "To further determine the suitability of NQO1 as a potential target against pancreatic cancer, we utilized the Oncomine database to evaluate its expression." (PMID 33214574, 2020). "Overexpression of NQO1 in solid cancers, including pancreatic cancer, is well-known; however, the actual mechanism driving high NQO1 expression remains elusive." (PMID 33214574, 2020). "In summary, KP372-1 sensitizes numerous NQO1-expressing pancreatic cancer cells, and spares immortalized normal pancreatic duct cells, hTERT-HPNE." (PMID 33214574, 2020). "Together, these data strongly support high levels of ROS production in NQO1-expressing pancreatic cancer cells after KP372-1 treatment." (PMID 33214574, 2020). "To systematically define the mechanistic basis of cytotoxicity, we sought to evaluate the production of ROS due to NQO1 redox cycling of KP372-1 in pancreatic cancer cells." (PMID 33214574, 2020). "Targeting NQO1:Catalase ratios of pancreatic cancers requires selective and potent NQO1 bioactivatable compounds." (PMID 33214574, 2020). "Overall, 109 pancreatic cancer specimens show significantly higher level of NQO1 expression compared to 70 normal pancreatic tissue (a total of 179 specimens)." (PMID 33214574, 2020). "We also noted the divergence of human pancreatic cancer cell lines, where NQO1 levels were substantially higher than in tumor tissue and Catalase levels are extremely varied." (PMID 26602448, 2015). "Loss or low activity of NQO1, by the reduction of its mRNA or the emergence of inactivating polymorphisms in the NQO1 gene, leads to resistance to 17-AAG in pancreatic cancer cells and glioblastoma cell lines." (PMID 26219569, 2015). "Here, we present a treatment strategy that makes BER inhibition tumor-selective and NQO1-dependent for therapy of most solid neoplasms, particularly for pancreatic cancer." (PMID 26602448, 2015). "The high NQO1/Catalase ratios in pancreatic cancers strongly suggest that NQO1-overexpressing PDA cancer cells will respond to NQO1 bioactivatable drugs by producing supralethal doses of H2O2." (PMID 26602448, 2015). "β-Lapachone, an NQO1 bioactivatable drug, is under clinical trial for pancreatic cancer treatment." (PMID 37570646, 2023). "Therefore, β-lap is a promising drug for selective treatment of not only pancreatic cancers, but many other NQO1 high tumors." (PMID 34789190, 2021). "Importantly, the majority of solid cancers including lung, colon, breast, and pancreatic cancer express elevated levels of NQO1, and these same tumors have significantly lowered Catalase (an H2O2 detoxifying enzyme) levels." (PMID 33214574, 2020). "Notably, we found that KP372-1 is ~ 10- to 20-fold more potent than β-lapachone, another NQO1 substrate, against pancreatic cancer cells." (PMID 33214574, 2020).
pancreatic cancer (continued). "Importantly, here we show that high NQO1 expression exclusively sensitizes a variety of pancreatic cancer cells to a novel NQO1 redox cycling agent KP372-1." (PMID 33214574, 2020). "In addition, inhibition of NQO1 with dicumarol induces oxidative stress and inhibits pancreatic cancer cell growth." (PMID 33158207, 2020). "Also, the mechanism of KP372-1-induced cytotoxicity delineated here for NQO1-overexpressing pancreatic cancer cells is likely to be similar for other NQO1+ solid cancers of lung, colon, breast, prostate and other tissues." (PMID 33214574, 2020). "There is still very little known as to why NQO1 is elevated in pancreatic cancers." (PMID 26602448, 2015). "The high expression of autophagy-related proteins, such as p62, WDFY3, and NQO1, in acinar cells near pancreatic steatosis, especially in acinar-ductal metaplasia and pancreatic cancer cells, indicates a link between autophagy disruption, oxidative stress, DNA damage, and pancreatic cancer." (PMID 39991930, 2025). "Indeed, NQO1 expression is an independent factor for poor pancreatic cancer prognosis." (PMID 37664430, 2023). "Interestingly, the central roles of Nqo1, Aox1, and Cxcl12 are demonstrated in pancreatic cancer." (PMID 35180880, 2022). "Here, we investigated this hypothesis by determining the suitability of targeting NQO1-expressing pancreatic cancer cells via KP372-1 and illustrated a previously unidentified mechanistic basis of cytotoxic effects of KP372-1 through instigating DNA damage response." (PMID 33214574, 2020). "The human pancreatic cancer cell line Panc-1, which has previously been genotyped as homozygous for the NQO1*2 polymorphism and characterized as NQO1 null, did not demonstrate detectable immunofluorescent staining for NQO1 either in the cytosol or mitotic spindles." (PMID 22984577, 2012). "The present study revealed that p62, WDFY3, NQO1, and LC3 were positive in the fatty area, ADM, and pancreatic cancer cells." (PMID 37664430, 2023). "Similar to LC3, we found that p62, WDFY3, and NQO1 were also strongly positive in ADM and pancreatic cancer cells." (PMID 37664430, 2023). "Taken together, these results demonstrate that NSLC01 is active against clinically relevant pancreatic cancer cell lines and ex vivo-cultured tumor tissues, with cytotoxic effects based on NRF2/NQO1 activation." (PMID 34247201, 2021). "After Bmi1 knockdown, the expression of antioxidant genes including CAT, MnSOD, GSTO1, NQO1 and SOD decreased significantly in pancreatic cancer cells." (PMID 27177084, 2016). "The NQO1/Catalase ratios demonstrated in pancreatic cancers (SF1) revealed a dramatic potential therapeutic window that can be exploited by NQO1 bioactivatable drugs, such as ARQ761 (ß-lapachone), currently in clinical trials (NCT01502800)." (PMID 26602448, 2015). "Previous immunohistochemical and transcriptomic studies report high NQO1 levels in pancreatic tumor tissues and cell lines, with markedly lower abundance in normal or benign pancreatic tissue NQO1 as a therapeutic target." (PMID 41007761, 2025). "Compared to normal tissue, NQO1 overexpression occurs up to 200-fold in >80% of non-small cell lung cancer (NSCLC), up to 100-fold in >80% of pancreatic cancer, up to 10-fold in 60% of prostate cancer, up to 10-fold in 60% of breast cancer, and up to 10-fold in 50% of colorectal cancer." (PMID 39120303, 2024). "Importantly, BPTES was observed to efficiently sensitize pancreatic cancer to 5-(tetradecyloxy)-2-furoic acid (TOFA, an acetyl-CoA carboxylase inhibitor) and ß-Lap (an NADPH:quinone oxidoreductase (NQO1) inhibitor) via enhancing cancer cell apoptosis." (PMID 35851420, 2022). "Notably, we found that KP372-1 is at least ~ 10- to 20-fold more potent than another NQO1 substrate, β-lap (ARQ761, under phase 1 clinical trials against pancreatic cancers, NCT02514031)." (PMID 33214574, 2020).
pancreatic cancer (continued). "Overall, our data strongly suggest that the potent redox cycling agent KP372-1 selectively induces cell death in NQO1-expressing pancreatic cancer cells and spares non-cancerous immortalized pancreatic duct cells." (PMID 33214574, 2020). "In recent years, NAD(P)H:quinone oxidoreductase-1 (NQO1, EC 1.6.99.2) is a flavoprotein overexpressed up to 5- to 200-fold compared to normal adjacent tissue in various solid tumors, including cancers of the pancreas, lung, prostate and breast, in terms of drug development." (PMID 28578385, 2017). "It was also shown that streptonigrin at 0.05 μM markedly decreased clonogenic survival of pancreatic cancer cells expressing NQO1 at elevated levels but not of colorectal cancer cells with lower levels of this enzyme." (PMID 24595456, 2014). "A549 NSCLC and MiaPaCa-2 pancreatic cancer cells expressing significant KRAS-driven NQO1 levels were hyper-sensitive to treatment with the PARPi rucaparib + KP372-1, but this sensitivity disappeared when the cancer cells were treated with the NQO1 inhibitor DIC." (PMID 36203459, 2022). "To strengthen the suitability of NQO1 as a promising target against pancreatic cancer, we evaluated NQO1 protein levels in five different commonly utilized model pancreatic cancer cell lines and one non-cancerous, immortalized pancreatic duct cell line, hTERT-HPNE." (PMID 33214574, 2020). "In addition, pre-treatment with 500 nM BPTES for 48 h did not increase the sensitivities of ß-lap-responsive, NQO1-expressing KRAS wild-type lung, breast, or pancreatic cancer cell lines, consistent with reported literature." (PMID 26462257, 2015).
colon carcinoma (40 papers, 1997 to 2025). "NQO1 plays a role in cell death, and absent or lowered NQO1 has been associated with increased susceptibility to cancer; however, NQO1 is upregulated in many cancers, including breast, pancreatic and colon cancer." (PMID 40566602, 2025). "On the other hand, mitomycin C-resistant human colon cancer cells were shown to harbour the NQO1*3 variant resulting in substantially reduced enzymatic activity." (PMID 28236663, 2017). "We have previously characterized a homozygous point mutation in the BE human colon carcinoma cell line that leads to a loss of NQO1 activity." (PMID 9000600, 1997). "Transcriptomic analysis in SFN‐exposed colon cancer cells revealed the non‐coding RNA Loc344887, regulated by Nrf2 and aiding NQO1 activity, identified as NMRAL2P." (PMID 40556338, 2025). "The proteins that interact with NQO1 are diverse, and a recent study revealed the NQO1-induced stabilization of hypoxia-inducible factor-1α (HIF-1α) in colon tumors from murine xenografts, via the mechanism of impaired proteasomal HIF-1α degradation." (PMID 34947831, 2021). "90% of pancreatic and NSCLC cancers have 10- to 100-fold of elevated levels of NQO1, and 60% of breast, prostate and colon cancers overexpress NQO1 5- to 20- fold." (PMID 34789190, 2021). "Increased protein levels of NRF2, NQO1 and HO-1 were also found in a melatonin-treated colon cancer model." (PMID 33805996, 2021). "The diversity of proteins which interact with NQO1 has grown significantly and recent work demonstrated stabilization of HIF-1α by NQO1 in RKO colon tumors in mice xenografts as a result of impaired proteasomal degradation." (PMID 28883796, 2017). "In a comprehensive study, these authors demonstrated that overexpression of NQO1 in RKO colon tumor xenografts led to significantly increased tumor growth rate and that knockdown of NQO1 inhibited growth but only in the context of functional HIF-1α." (PMID 28883796, 2017). "Human colon tumors (implanted HCT116 cells) were sensitized towards MMC by feeding mice the NQO1 inducer dimethyl fumarate." (PMID 26950072, 2016). "In conclusion, UGT1A is an important determinant, via switching NQO1-triggered redox cycle to metabolic elimination, in the intracellular accumulation of β-lap and thereafter its cytotoxicity in human colon cancer cells." (PMID 25692465, 2015). "Intestinal-specific STEAP4 overexpression in mice is associated with increased mitochondrial iron accumulation, heightened oxidative stress-responsive protein NAD(P)H quinone dehydrogenase 1 (NQO1) and augmented susceptibility to colon tumors." (PMID 40205952, 2025). "Moreover, NQO1 mRNA expression negatively correlated with STEAP4 mRNA expression in colon tumor tissues." (PMID 40205952, 2025). "Notably, bioactivatable drugs targeting NQO1 were highly effective at eradicating STEAP4-overexpressing colon cancer cells." (PMID 40205952, 2025). "This decrease in STEAP4 expression in colon tumors contrasts with our previous findings, highlighting the complexity of the relationship between STEAP4 and NQO1 and the need for further investigation." (PMID 40205952, 2025). "Ongoing research underscored the overexpression of NQO1 in several aggressive cancers, with its heightened levels being inversely related to survival rates, especially in NSCLC, breast, and colon cancers." (PMID 38136388, 2023). "The Nrf2 target genes, such as heme oxygenase-1 (HO-1) and NAD(P)H-quinone oxidoreductase-1 (NQO1) are reported to mediate chemotherapy resistance in several cancers, including gastric and colon cancers." (PMID 34249773, 2021).
colon carcinoma (continued). "FaDu human pharynx squamous carcinoma cells had a high level of NQO1 activity, 557.6 ± 120.3 nmol.min−1.mg protein−1, while HCT116 human colon carcinoma cells had a level of NQO1 activity that was close to the average for human tumors, 230.4 ± 31 nmol.min−1.mg protein−1." (PMID 21904446, 2009). "Notably, NQO1 bioactivatable quinone drugs, specifically β-lapachone (β-LPC) and KP372-18, outperform the conventional 5-fluorouracil (5-FU) in terms of killing efficiency in STEAP4-overexpressing colon tumor cells." (PMID 40205952, 2025).